NLRP3 (NLR family pyrin domain containing 3)
Diseases named in the same sentence as NLRP3 in open-access papers (continued):
Sharing a sentence is not in itself a finding about the gene and the disease.
myelodysplastic syndrome (21 papers, 2020 to 2024). A clonal hematopoietic disorder characterized by dysplasia and ineffective hematopoiesis in one or more of the hematopoietic cell lines. "Recently, a study showed that the activation of the cGAS/STING/NLRP3 axis by cytoplasmic DNA in Tet2-deficient hematopoietic stem/progenitor cell line promotes myelodysplastic neoplasms development." (PMID 37816954, 2023). "Functionally different mutations have converged to form the cGAS/STING/NLRP3 axis in myelodysplastic syndrome (MDS, a group of cancers in which blood cells are poorly formed and do not work typically) to direct ISG production, pyroptosis, and myeloid lineage skewing." (PMID 38339107, 2024). "Equally, the importance of NLRP3 activation in the pathogenesis of myelodysplastic syndromes (MDS) is well established." (PMID 37418424, 2023). "Myelodysplastic Syndromes (MDSs) are bone marrow (BM) failure malignancies characterized by constitutive innate immune activation, including NLRP3 inflammasome driven pyroptotic cell death." (PMID 36835307, 2023). "Notably, NLRP3 inflammasome activation in myelodysplastic neoplasms occurs mainly through the TLR4 pathway." (PMID 35897704, 2022). "Since NLRP3 inflammasome activation in HSCs as well as other innate cells in the bone marrow is integral to bone marrow aging and myelodysplastic syndromes, targeting NLRP3 is an interesting possibility to reverse inflamm-aging and promote homing and engraftment in transplant settings." (PMID 35198558, 2022). "S100A9 activates the ROS-dependent NLRP3 inflammasome and induces pyroptotic cell death and clonal expansion of HSPCs in myelodysplastic syndrome (MDS) patients." (PMID 38764093, 2024). "Other very important participating factors, the NLRP3 and AIM2 inflammasomes, have appeared as crucial players in regulating certain hematological pathologies, e.g., myelodysplastic syndrome (MDS), MPNs, cardiovascular risk, and leukemia." (PMID 35328626, 2022). "S100A9 mediates NLRP3 inflammasome activation in the HSPCs of patients with myelodysplastic syndrome (MDS), which induces clonal expansion and pyroptotic cell death." (PMID 34801085, 2021). "NLRP3 inflammasome, pyroptosis and cGAS-STING contribute to neuroinflammation in myelodysplastic syndromes (MDSs) and spinal cord injury (SCI)." (PMID 38195584, 2024). "Several hematological diseases, such as myelodysplastic syndrome (MDS), myeloproliferative neoplasms, leukemias, lymphomas and graft-versus-host diseases (GvHD), are also impacted by the NLRP3 inflammasome." (PMID 36902299, 2023). "Under aberrant conditions, the NLRP3 inflammasome is associated with many autoinflammatory and metabolic disorders, including cryopyrin‐associated periodic syndromes (CAPS), myelodysplastic syndromes (MDS), obesity, type‐2 diabetes and Alzheimer's disease." (PMID 35832835, 2022). "NLRP3 inflammasome and IFN-stimulated gene (ISG) induction are key biological drivers of ineffective hematopoiesis and inflammation in myelodysplastic syndromes (MDSs)." (PMID 35788117, 2022). "BM stromal cells from patients with myelodysplastic syndrome display a senescence phenotype induced by S100A9-induced Toll-like receptor 4 (TLR4), NLR family pyrin domain containing 3 (NLRP3) inflammasome activation, and IL-1β secretion." (PMID 33299638, 2020). "Moreover, the cGAS-STING pathway was activated in myelodysplastic syndromes (MDS) to induce IFN-stimulated genes (ISG), which triggered the activation of NLRP3 inflammasome." (PMID 38195584, 2024). "The NLRP3 inflammasome correlated with the pathogenesis of non-Hodgkin lymphomas, multiple myeloma, acute myeloid leukemia, lymphoid leukemias, myelodysplastic neoplasms, graft-versus-host-disease, and sickle cell anemia." (PMID 35897704, 2022).
neuropathy (21 papers, 2017 to 2026). A disorder affecting the nervous system that manifests with pain, tingling, numbness, and/or muscle weakness. "The purinergic receptor P2X7 (P2X7R)/NLRP3 inflammasome axis has emerged as a master regulatory node implicated across diverse neuropathies." (PMID 41574659, 2026). "It has been reported that PTX induces the activation of Nod-like receptor protein 3 (NLRP3) inflammasome, and this stimulation is associated with the onset of neuropathy." (PMID 39061924, 2024). "However, only a few studies have evaluated the contribution of NLRP3 to the neuropathy caused by chemotherapy." (PMID 40002330, 2025). "Accordingly, inhibition of the IL‐1 receptor using anakinra or the NLRP3 inflammasome using the small molecule NLRP3 inhibitor MCC950 prevented sensory–motor neuropathy following vincristine monotherapy in mice." (PMID 40104043, 2025). "This interaction is further reinforced by the normalization of the up-regulation of NLRP3 induced by HRW in the dorsal root ganglia of animals with PTX-induced neuropathy." (PMID 40002330, 2025). "Previous studies have demonstrated that linarin prevents dry eye disease and neuropathy by inhibiting inflammation through the TXNIP/NLRP3 inflammasome pathway." (PMID 40265676, 2025). "The high levels of P2X4 and NLRP3 in STZ treated rats suggested that cytokines are involved in neuropathy." (PMID 31859818, 2019). "In recent years, it has become apparent that neuroinflammatory processes mediate VIPN, and specifically, that vincristine leads to activation of the NLRP3 inflammasome in monocytes, which in turn affects the release of IL‐1β that drives neuropathy symptoms, such as sensory and motor disturbances." (PMID 40104043, 2025). "None of the immune markers demonstrated a correlation with hearing function as an indicator of tumor induced neuropathy, a finding consistent with the majority of published literature, which highlights only isolated targets such as NLRP3 inflammasomes as correlating with hearing function." (PMID 38817895, 2024). "Therefore, natural product research is still needed through the regulation of NLRP3 inflammasome assembly in a wide range of neuropathies to identify various pharmacological mechanisms and develop therapeutic agents for such neuropathies." (PMID 33525754, 2021). "For instance, bortezomib, a proteasome inhibitor, promoted histone H3 and H4 acetylation on the NLRP3 promoter via STAT3, resulting in the upregulation of NLRP3 expression in dorsal root ganglion, a potential mechanism for bortezomib-induced painful neuropathy." (PMID 32796686, 2020). "Thus, the inhibition of IL-1β by melatonin reported here suggests that the neuroinflammatory process in CMT1A neuropathy involves both NF-κB and NLRP3 inflammasome." (PMID 29036910, 2017). "It is worth mentioning that our conclusions are based on observations in two different animal models of Aβ-associated neuropathy (APP/PS1 and AppNL-G-F mice), and involved both microglia-selective as well as constitutive full body deletion of core inflammasome components (caspase-1 and Nlrp3)." (PMID 38352874, 2024). "The work presented here suggests that the Nlrp3 inflammasome is not critically involved in shaping microglial activation states or in driving Aβ-induced neurodegeneration in preclinical models of Aβ-associated neuropathy." (PMID 38352874, 2024). "In addition, chemotherapy-induced neuropathy models of neuropathic pain revealed that NLRP3 is upregulated in both oxaliplatin-induced nerve injury and paclitaxel-induced nerve injury models, and inhibition of NLRP3 decreased the mechanical pain-like behaviors in both models." (PMID 31244767, 2019). "Activation of the microglial Nlrp3 inflammasome has been proposed as a key contributor to the progression of AD pathology in the APP/PS1 and CRND8-APP models of Aβ-induced neuropathy." (PMID 38352874, 2024).
neuropathy (continued). "Previous studies found that NLRP3 inflammasome activation and downstream DRG inflammation led to painful neuropathy, lumbar disc herniation, and bortezomib-induced mechanical allodynia in type 2 diabetic rodents." (PMID 34803664, 2021). "NLRP3 inflammasome activation and IL-1β release have been observed in the DRG of mice with high-fat diet induced prediabetic neuropathy and palmitate-treated DRG neurons." (PMID 34803664, 2021). "Considering the crucial role of inflammation and oxidative stress in the development of neuropathy after PTX chemotherapy, we evaluated the impact of the pharmacological inactivation of the NLRP3 inflammasome on the expression of markers of oxidative stress, synaptic plasticity, and apoptosis." (PMID 40002330, 2025). "From upstream regulators (P2X7R, CXCR4, TBK1) and core inflammasome components (NLRP3) to effector caspases (caspase‐1) and the final executors (GSDMD), each node offers a leverage point for intervention, with evidence spanning multiple etiologies of neuropathy." (PMID 41574659, 2026). "Similarly, studies that tested the effects of NLRP3 inhibition for the treatment of chemotherapy‐induced neuropathy failed to assess these effects in tumor‐bearing animals." (PMID 40104043, 2025). "Several studies have further indicated that NLRP3 inflammasome inhibition could be an approach for treating chronic pain, but its impact on the anxiodepressive-like behaviors and memory deficits related to PTX-provoked neuropathy has not yet been investigated." (PMID 40002330, 2025).
breast tumor (20 papers, 2019 to 2025). "In this study, we evaluated novel 3D scaffolds based on GelMA and two distinct types of pectin enriched with PTX–cyclodextrin inclusion complexes for their ability to inhibit the growth of breast tumor cells and stimulate NLRP3-associated pyroptosis." (PMID 39940603, 2025). "In NLRP3‐deficient mice, the growth and metastasis of breast tumor cells were inhibited by reduced MDSCs infiltration." (PMID 38116060, 2023). "Another study indicated that NLRP3 expression in infiltrating macrophages was significantly associated with survival and metastasis in human breast tumor via S1PR1 signaling." (PMID 34211462, 2021). "Moreover, the breast tumor microenvironment is associated with NLRP3 inflammasome activation, characterized by pyroptosis cell death and the release of pro-inflammatory cytokines." (PMID 39940603, 2025). "Recent studies revealed that only NLRP3 silencing suppressed breast tumor cells proliferation and induced cell death, which represents an advantage for obtaining a favorable post-chemotherapeutic response." (PMID 39433537, 2024). "Firstly, the researchers demonstrated the NLRP3 knockdown results in a decrease in breast tumor cell proliferation and migration, due to apoptosis initiation." (PMID 36834660, 2023). "The heterogeneity of the breast tumor microenvironment triggers the interest of non-coding RNAs’ involvement in NLRP3 inflammasome assembly, TNBC progression and metastasis." (PMID 36834660, 2023). "In an effort to validate the role of NLRP3 in breast tumor growth, it was discovered that blocking the IL-1β receptor promotes apoptosis and prevents cell cycle progression in cancer cells." (PMID 37715239, 2023). "In primary breast tumors, both in mouse and human carcinomas, NLRP3 activation was primarily observed in host cells, specifically in cancer-associated fibroblasts (CAFs)." (PMID 37749707, 2023). "In the context of this disease, it has been revealed that IL-1 and NLRP3 were overexpressed in the breast tumor microenvironment concomitant with the increase of MDSCs and TAMs." (PMID 37715239, 2023). "MiR-205 supports breast tumors’ growth and inhibits apoptosis due to its capacity to mediate the assembly mechanism of the NLRP3 complex." (PMID 36834660, 2023). "Breast tumor growth, progression and aggressiveness are promoted by NLRP3 inflammasome activation, pro-inflammatory cytokine secretion and the pyroptotic death of cancer cells." (PMID 36834660, 2023). "Inflammasome NLRP3 activation, pro-inflammatory cytokine production, and pyroptotic death of cancer cells promote breast tumor growth, progression, and aggressiveness." (PMID 37300757, 2023). "Although other sources of NLRP3 are possible, this study showed a clear induction of IL-1β production in myeloid cells by breast tumor cells." (PMID 35631400, 2022). "Here, we expanded upon those findings by using genetic and pharmacological NLRP3 inhibition to elucidate NLRP3 as the predominate inflammasome sensor responsible for breast tumor-induced IL-1β production in infiltrating myeloid cells." (PMID 35631400, 2022). "Other groups have found that knocking out Nlrp3 and Casp1 in mice significantly reduces the growth of primary breast tumours and lung metastases compared with wild-type mice." (PMID 36230739, 2022). "In an attempt to further validate the role of the NLRP3 in breast tumor growth, it was observed that blockade of IL-1β receptor promotes apoptosis and prevents cell cycle progression in cancer cells." (PMID 33840390, 2021). "It is also interesting to note that leptin, another well-known adipokine, promotes breast tumor growth through NLRP3 inflammasomes activation." (PMID 32155890, 2020). "Our findings implicate activation of the NLRP3 inflammasome in CAFs in promoting the recruitment of MDSCs to breast tumours and to lung metastases, thus supporting the formation of an immunosuppressed microenvironment." (PMID 31558756, 2019).
breast tumor (continued). "Therefore, the aim of this study was to obtain a biocompatible 3D porous biosystem enriched with an anti-tumor component designed to inhibit breast tumor cells and induce pyroptosis by activating the NLRP3 inflammasome." (PMID 39940603, 2025). "In addition to supporting breast tumor growth, MiR-205 inhibits apoptosis through its role in NLRP3 complex assembly." (PMID 37300757, 2023). "Moreover, anatomical experiments analyzing 53 breast tumor patients revealed a significant upregulation of gene expression in the NLRP3 inflammasome pathway in human breast tumor stroma compared to normal tissue stroma, suggesting an non-negligible role for this pathway in tumor progression." (PMID 38317229, 2024). "It has been reported that anti-breast tumour chemotherapy efficacy relies on myeloid PTEN, which directly interacts with and dephosphorylates NLRP3 to facilitate interaction with ASC and inflammasome activation." (PMID 32883606, 2020). "Here, the authors show that CAFs sense tissue damage and activate NLRP3 inflammasome and pro-inflammatory IL-1β secretion, and CAF-derived inflammasome signalling promotes breast tumour growth and metastasis." (PMID 31558756, 2019). "Additionally, microwave-responsive AlEu-MOFs amplify NLR Family Pyrin Domain Containing 3 (NLRP3) inflammasome activation through HSP90 upregulation and ROS generation, achieving targeted pyroptosis to inhibit primary and metastatic breast tumors." (PMID 41235238, 2025). "Analysis revealed a significant up-regulation in the expression of genes from the NLRP3 inflammasome pathway (NLRP3, PYCARD, CASP1, and IL-1β) in the stroma of human breast tumours compared with normal stroma, suggesting a functional role for this pathway in tumour progression." (PMID 31558756, 2019).
E. coli infection (20 papers, 2017 to 2025). "E. coli infection triggers the inflammasome-mediated pathway, which, in turn, activates inflammatory responses and cell death, such as NLRP3 and Apoptosis-associated Speck-like protein containing a CARD (ASC)." (PMID 41415272, 2025). "Further studies are required to determine active components derived from L. rhamnosus GR-1 and elucidate possible mechanisms underlying the antagonistic effects of L. rhamnosus GR-1 on NLRP3 activation during E. coli infection." (PMID 30087667, 2018). "In mice, non-canonical caspase-11 was identified as a key regulator of NLRP3 inflammasome-associated caspase-1 activation in response to E. coli infection." (PMID 30087667, 2018). "Collectively, our data implicate that CVB3 infection could increase the susceptibility of mice to E. coli infection, possibly by inhibiting the activation of the NLRP3 inflammasome and the production of IL-1β." (PMID 37243164, 2023). "In this study, E. coli infection resulted in autophagy inhibition in PMECs, which might cause enhanced NLRP3-ASC assembly and ROS generation." (PMID 32823867, 2020). "In LPS or E. coli infection, Txnip-deficient macrophages manifest the partial decrease of active caspase-1 and IL-1β production, which might result from increased S-nitrosylation of NLRP3 inflammasome components that hinder IL-1β maturation." (PMID 31620121, 2019). "Mechanistically, our results suggest the involvement of the NLRP3/caspase-1/GSDMD pathway in E. coli infection." (PMID 37511208, 2023). "We also investigated the mRNA levels of the genes involved in the NLRP3/caspase-1/GSDMD pathway in cells after E. coli infection and found that ZB-1 infection significantly upregulated their expression levels." (PMID 37511208, 2023). "Given the critical role of NLRP3 in E. coli infection, we conducted a search in existing drug databases to identify the compounds that target NLRP3." (PMID 37511208, 2023). "Next, we measured the mRNA levels of each gene in the NLRP3/caspase-1/GSDMD pathway after E. coli infection." (PMID 37511208, 2023). "To further elucidate the mechanism of pyroptosis induced by E. coli infection, we mined the dataset (GSE124917) in the GEO database and found that E. coli infection significantly upregulates NLRP3, caspase-1, GSDMD, and IL-1β." (PMID 37511208, 2023). "We also observed the assembly of NLRP3 inflammasomes in the intestine, which was significantly promoted by E. coli infection, especially in the Ybt-producing ZB-1 group." (PMID 37511208, 2023). "Protein interaction network analysis revealed that the pyroptosis classic pathway NLRP3/caspase-1/GSDMD is involved in E. coli infection." (PMID 37511208, 2023). "Collectively, our data indicate that Z. morio hemolymph limits detrimental inflammatory responses partly by regulating the NLRP3 inflammasome pathway through ATG5/ATG16L1-mediated autophagy pathway during E. coli infection." (PMID 36362066, 2022). "PAK1 also regulates NLRP3 at Thr659 during E. coli infection, suggesting PAK1 regulates multiple inflammasome proteins during bacterial infection." (PMID 34854899, 2021). "Mean CSF NLRP3 (ng/ml) was 2,124 ± 1,396 for S. pneumoniae infection, 2,606 ± 1,497 for K. pneumoniae infection, 2,181 ± 2,386 for E. coli infection, and 1,213 ± 996.9 for L. monocytogenes infection." (PMID 35145923, 2021). "E. coli infection induced NOD-like receptor family member pyrin domain-containing protein 3 (NLRP3) inflammasome assembly, Caspase-1 activation, and apoptosis in MAC-T cells." (PMID 34594329, 2021). "As shown, the expression level of NLRP3 was significantly lower in the hemolymph-treated group (2 mg/mL for E. coli and 4 mg/mL for S. simulans) than the control group after E. coli infection." (PMID 32998225, 2020).